NPM3 (nucleophosmin/nucleoplasmin 3)
Description:
Plays a role in the regulation of diverse cellular processes such as ribosome biogenesis, chromatin remodeling or protein chaperoning. Modulates the histone chaperone function and the RNA-binding activity of nucleolar phosphoprotein B23/NPM. Efficiently mediates chromatin remodeling when included in a pentamer containing NPM3 and NPM.
Synonyms: PORMIN
Tractability: PROTAC: ubiquitination databases record sites on it; its protein half-life has been measured.
Gene: Protein-coding gene on chromosome 10 (101,781,318 to 101,783,446, reverse strand). Ensembl gene ENSG00000107833.
Subcellular location: Nucleus; Nucleus, nucleolus
Subcellular location (Human Protein Atlas): Actin filaments; Cytosol; Nucleoli
Gene Ontology:
Molecular function: protein binding; RNA binding; chromatin binding; histone binding
Biological process: chromatin remodeling
Cellular component: cytoplasm; nucleolus; nucleoplasm; nucleus
Genetic constraint (gnomAD): Loss-of-function variants: 12 observed, 18.84 expected, observed/expected ratio (o/e) 0.64, 90% interval 0.41 to 1.03. The upper end of that interval is the gene's LOEUF score, 1.03, which puts it in group 4 of 6, group 1 being the genes least tolerant of losing a copy. Missense variants: 274 observed, 247.05 expected, observed/expected ratio (o/e) 1.11, 90% interval 1 to 1.23. Synonymous variants: 116 observed, 97.74 expected, observed/expected ratio (o/e) 1.19, 90% interval 1.02 to 1.38.
Homologues: Orthologues: chimpanzee NPM3 (100% identical), macaque NPM3 (99% identical), rabbit NPM3 (92% identical), pig NPM3 (89% identical), guinea pig NPM3 (87% identical), mouse Npm3 (81% identical), dog NPM3 (81% identical), rat Npm3 (81% identical), tropical clawed frog npm3 (44% identical), zebrafish npm3 (40% identical), Drosophila melanogaster Nlp (24% identical), Drosophila melanogaster Nph (23% identical). Paralogues in human: NPM1 (36% identical), NPM2 (36% identical).
Diseases named in the same sentence as NPM3 in open-access papers:
NPM3 is named in the same sentence as 13 diseases in open-access papers, as found by Europe PMC text mining. Sharing a sentence is not in itself a finding about the gene and the disease. The quoted sentences say what the papers report.
lung carcinoma (2 papers, 2023). "Accordingly, NPM3 inhibitors might be useful for prostate and lung cancer therapy." (PMID 37870957, 2023).
colorectal cancer (1 paper, 2024). A primary or metastatic malignant neoplasm that affects the colon or rectum. "Taken together, our proteomic screen suggests a common mechanism of AGR2 acting over FLNA and NPM3 proteins in SW480 and SW620 colorectal cancer cell models, as demonstrated by both the overexpression and silencing of AGR2." (PMID 39300184, 2024).
gastric cancer (1 paper, 2024). A primary or metastatic malignant neoplasm involving the stomach. "In lung adenocarcinoma, NPM3 is positively correlated with proliferation, while in gastric cancer, it promotes PD-L1-mediated immune escape." (PMID 39300184, 2024). "Since NPM3 was recently described to be involved in regulating PD-L1 expression in gastric cancer through binding to NPM1 and promoting its binding to the PD-L1 promoter, we analysed PD-L1 expression at the mRNA level." (PMID 39300184, 2024).
lung adenocarcinoma (1 paper, 2023). A carcinoma that arises from the lung and is characterized by the presence of malignant glandular epithelial cells. "The aim of this study was to investigate the expression and function of NPM3 in the tumor microenvironment of lung adenocarcinoma (LUAD)." (PMID 37254219, 2023). "To investigate the role of NPM3 in lung adenocarcinoma, we examined the effect of NPM3 on cell proliferation." (PMID 37254219, 2023).
Obesity (1 paper, 2022). Accumulation of substantial excess body fat. "sEVs-BAT enhanced the expressions of browning related genes in 3T3-L1 preadipocytes and WAT while knocking down of NPM3 in BAT impaired sEVs-BAT mediated WAT browning and weight loss in obesity." (PMID 35346213, 2022). "In this study, we identified the critical role of NPM3 in the regulation of WAT browning and amelioration of HFD (high-fat diet) induced obesity, the results implicated a potential anti-obesity strategy in the future." (PMID 35346213, 2022). "In obesity, we noted that the expression level of NPM3 was significantly decreased in the iWAT, eWAT and BAT of the ob/ob mice compared to the lean mice." (PMID 35346213, 2022). "A previous study reported that sEVs-BAT could be used to combat obesity, considering the role of NPM3 in WAT browning, we asked whether NPM3 could make a contribution in sEVs-BAT mediated obesity combating." (PMID 35346213, 2022). "Although the NPM family was found to be associated with a variety of endocrine and metabolic dysregulation, such as aerobic glycolysis, insulin receptor expression, obesity and aging, the biological functions of NPM3 were largely undefined, especially for the regulation of adipose tissue itself." (PMID 35346213, 2022).
prostate carcinoma (1 paper, 2023). A carcinoma that arises from epithelial cells of the prostate gland. "Moreover, we found that NPM3 was overexpressed in prostate cancer and might be indicative of disease aggressiveness." (PMID 37870957, 2023).
prostate tumors (1 paper, 2023). "Bioinformatics revealed that NPM3 mRNA is upregulated in prostate tumors and even more so in metastases." (PMID 37870957, 2023). "Our data show that NPM3 is overexpressed in prostate tumors and marks aggressive disease, suggesting that NPM3 drives prostate tumorigenesis." (PMID 37870957, 2023). "We corroborated that NPM3 is also overexpressed at the protein level in prostate tumors." (PMID 37870957, 2023).
tumor (3 papers, 2023 to 2025). "Single-cell sequencing analysis revealed that NPM3 was expressed in immune cells (dendritic cells and monocytes/macrophages) in the tumor microenvironment." (PMID 37254219, 2023). "Overall, we found that NPM3 was positively associated with genes that promote tumor proliferation, with NPM3 positively regulating the expression of CCNA2 and MAD2L1, and NPM3 was negatively correlated with the tumor suppressor RASSF5." (PMID 37254219, 2023). "We anticipate that further studies will shed light on the action pattern of NPM3 in the LUAD tumor microenvironment." (PMID 37254219, 2023). "To determine the differences of NPM3 expression between normal and tumor tissues, we analyzed the NPM3 mRNA expression in TCGA-LUAD and GTEx samples using the UALCAN and GEPIA2 databases." (PMID 37254219, 2023). "Collectively, a comprehensive analysis of immune cell infiltration, immune checkpoint expression, and cell function experimental results suggests that high NPM3 expression is more probably mediating the immunosuppressive microenvironment to promote tumor progression." (PMID 37254219, 2023). "In summary, NPM3 is highly expressed and positively correlated with tumor malignancy in LUAD." (PMID 37254219, 2023). "In this study, we comprehensively investigated the expression and function of NPM3 in LUAD and its relationship with the tumor microenvironment." (PMID 37254219, 2023). "Consistently, NPM3 downregulation inhibited DU145 cells both in vitro and in vivo, leading to reduced tumor formation at the primary injection site as well as in the lung." (PMID 37870957, 2023). "We believe that NPM3 plays a more important role in the initial stage of tumor immunity and immune regulation, rather than in the effector phase." (PMID 37254219, 2023). "Based on the significantly elevated expression of NPM3 in LUAD samples and its positive correlation with tumor malignancy, it is possible that NPM3 may have a negative impact on patient survival." (PMID 37254219, 2023). "However, the effect of NPM3 on LUAD progression and its relationship with the tumor microenvironment are not yet clear." (PMID 37254219, 2023).
cancer (2 papers, 2023 to 2024). A tumor composed of atypical neoplastic, often pleomorphic cells that invade other tissues. "NPM3 is emerging as a significant player in tumorigenesis and cancer progression." (PMID 39300184, 2024). "This is the first report of NPM3 expression in various cell clusters used for cancer research." (PMID 37254219, 2023). "There is only one report implicating that NPM3 might engage in cancer proliferation as a novel target of transcription factor SP1 in Hela cells." (PMID 37254219, 2023).
prostate (1 paper, 2023). "Finally, we identified NPM3 as a downstream effector of JMJD2A and revealed that NPM3, in its own right, can promote prostate tumorigenesis." (PMID 37870957, 2023).
NPM3 also shares sentences with these, for which no sentence is quoted: cervical cancer (1 paper); leukoplakia (1); T-cell lymphomas (1).